PGR (progesterone receptor)
Diseases named in the same sentence as PGR in open-access papers (continued):
Sharing a sentence is not in itself a finding about the gene and the disease.
tumor (continued). "The tumor was both estrogen-receptor and progesterone-receptor positive (ER+/PR+) with Allred scores of 8 and 3, respectively." (PMID 23198815, 2012). "The available clinical variables included age, diameter, tumor grade, angioinvasion, oestrogen and progesterone receptor status, and lymphocytic infiltration." (PMID 22824262, 2012). "Tumor stage, histological grading, estrogen and progesterone receptor (ER and PgR), proliferative index and human epidermal growth factor receptor 2 (HER2) aid in tumor evaluation and often dictate the choice of systemic treatment." (PMID 22672524, 2012). "The presence of tumor infiltrating lymphocytes (TILs) as well as progesterone receptor (PR) positivity has been correlated with improved prognosis." (PMID 22295114, 2012). "Only RASSF1A was associated with worse time to first recurrence (p = 0.045) and worse overall survival (p = 0.016) after adjusting for age, tumor size, S-phase, estrogen receptor and progesterone receptor." (PMID 22695491, 2012). "Positive correlations were found between tumour size (T), regional lymph node status (N) and distant metastasis (M); between ER and PGR status; and between HER2 status, tumour size (T) and distant metastasis (M)." (PMID 23028444, 2012). "Most tumours were ER and PgR positive, with 89.7% (52/58) and 77.2% (44/57) of cases respectively scored as high (Allred score 6-8/8)." (PMID 23146383, 2012). "GP88 remained an independent risk predictor after considering age, ethnicity, nodal status, tumor size, tumor grade, disease stage, progesterone receptor expression and treatments." (PMID 22316048, 2012). "30–67% of CRC tumours are oestrogen receptor (ER) positive and 10–100% are progesterone receptor (PR) positive." (PMID 23097739, 2012). "Both carcinomas were positive for oestrogen receptor (ER) and progesterone receptor (PR) expression in the majority of tumour cells, and also overexpressed the human epidermal growth factor receptor (HER2/neu)." (PMID 22672556, 2012). "Prognostic factors, for example, estrogen and progesterone receptor status, and tumor stage were recorded." (PMID 22594557, 2012). "Immunohistochemical analysis was done on tumor sections using antibodies to progesterone receptor, Ki67 and cleaved caspase-3." (PMID 22911820, 2012). "For example, tumor grades and estrogen/progesterone receptor status can provide additional and significant contributions to such heterogeneity." (PMID 22629394, 2012). "Recent retrospective reviews have shown discordance between the primary tumor and metastases in 14%-48% for ER and PgR status, and in 2%-13% for HER-2 status." (PMID 22059982, 2011). "Seventy percent of patients had oestrogen receptor (ER) positive tumours, and 47% had progesterone receptor (PR) positive tumours." (PMID 22091423, 2011). "Clinically, tumors are classified on the basis of tumor size, visual characteristics, and a limited number of histochemical markers including estrogen receptor, progesterone receptor and HER2 receptor status." (PMID 21672245, 2011). "In this case series, patient age, lymph node involvement and PgR status were significant predictors of relapse-free survival at seven years of follow-up, whereas large tumor size and high histological grade were only suggestive of an unfavorable prognosis." (PMID 24212666, 2011). "In the subset of 203 patients with invasive cancer, YKL-40 levels were positively correlated with tumour grade (P<0.0001) and Her2/neu (P<0.01), but negatively correlated with oestrogen (P<0.0001) and progesterone receptor (P<0.0001)." (PMID 21934681, 2011). "An Allred score of 7 or 8 for progesterone receptor in the tumour cells had a significantly lower hazard ratio for tumour-related death in multivariate analysis." (PMID 21811256, 2011).
tumor (continued). "A multivariate analysis revealed that the status of distant metastasis and PgR level at relapse, and Ki-67 levels at primary tumor were all significant factors." (PMID 22004841, 2011). "Multivariable analysis revealed that Ki-67 at primary tumor and PgR at relapse are significant factors in post-relapse prognosis." (PMID 22004841, 2011). "The hormone receptor positive rate from the primary tumor to recurrence decreased from 63.9% to 57.7% and from 56.7% to 43.3% for ER and PgR, respectively." (PMID 22004841, 2011). "Approximately two-third of breast cancers are influenced by activation of estrogen receptor (ER) pathway and expressing ER and/or progesterone receptor (PR) in the tumor nuclei." (PMID 21221174, 2010). "DC-SCRIPT levels were positively associated with tumor grade and ESR1, PGR, and ESR2 steroid hormone receptor expression level and negatively associated with invasive epithelial tumor cell content and tumor size." (PMID 21122099, 2010). "Tumor cells were examined by flow cytometry for expression of estrogen receptor α, progesterone receptor, androgen receptor, her-2/neu, epithelial cell adhesion molecule, and CA125." (PMID 20356397, 2010). "CDO1 DNA methylation was a significant marker in the pairwise multivariate analysis including age at surgery, pathological T stage, progesterone receptor status, tumor grade or endocrine therapy." (PMID 20515469, 2010). "We next performed immunohistochemical staining of tumour sections with antibodies against ER and PgR." (PMID 20723242, 2010). "We found HER2 to be up-regulated by 1.5 fold (p = 0.0054) and PGR to be down-regulated by 1.9 fold (p = 0.006) in tumor compared to adjacent normal tissue." (PMID 21059268, 2010). "Tumor grade, size, estrogen and progesterone receptor status, and triple negative status were significantly (Q-values <0.05) associated with altered methylation of 209, 74, 183, 69, and 130 loci, respectively." (PMID 20686660, 2010). "From the histopathological parameters (tumour size, lymphnode status, histological grade, oestrogen, and progesterone receptor status), only tumour size was significantly correlated (P=0.015) with the mean number of PLA signals." (PMID 20700126, 2010). "The available clinical variables are age (metric), tumor grade (ordinal), estrogen receptor status (binary), progesterone receptor status (binary), tumor size (metric) and angioinvasion (binary)." (PMID 20144191, 2010). "For example, there are differences in tumour grade and estrogen and progesterone receptor (ER and PR) positivity between black, Hispanic and white women in the US." (PMID 21138590, 2010). "Hormonal therapies were not included in the calculation of the cost-effectiveness because, per the tac-fac study, tamoxifen was administered on completion of chemotherapy to patients with estrogen or progesterone receptor–positive (or both) tumours." (PMID 20179798, 2010). "Our results suggest that PgR expression represents a clinical surrogate marker for tumor expression of 4ICD, a potent ERα coactivator and regulator of tamoxifen action." (PMID 20550710, 2010). "The data on PgR status does not support its use as a selection criterion in the context of ER positivity, and PgR+ ER− tumours are too uncommon to make a definitive statement with regard to their management." (PMID 20700118, 2010).
tumor (continued). "In the combined analysis histological tumor size, grade, number of positive nodes, progesterone receptor status and treatment combination are prognostic factors of any event." (PMID 21194468, 2010). "For all samples, sex, age, diagnosis, pathological tumour-node-metastasis (pTNM), stage, lymph node (positive lymph nodes/examined lymph nodes) as well as progesterone receptor (PR) and oestrogen receptor (ER) expression status were available." (PMID 19243594, 2009). "For example, a recent article associated expression of GAS6 with indicators of good prognosis such as progesterone receptor positivity, small tumor size, low grade, and young patient age." (PMID 19995430, 2009). "An estrogen receptor and progesterone receptor study has been done to verify the hormonal basis of this tumour." (PMID 19829968, 2009). "Compared with normal weight women, obese women more often had large tumours, lymph node positivity, and progesterone receptor-positive tumours." (PMID 19367278, 2009). "The expression status of oestrogen receptor, progesterone receptor and c-erbB2 in tumour tissue was also reflected in serum levels of analytes." (PMID 19400944, 2009). "Nuclear YB-1 detection also correlated with tumor stage (p = 0.004), higher (G2/G3) histological grade (p = 0.011) and negativity of progesterone receptor status (p = 0.002)." (PMID 19930682, 2009). "mtDNA content was correlated with tumor stage, menstruation status, and age of patients as well as lymph node status and the expression of estrogen receptor (ER), progesterone receptor (PR) and Her-2/neu protein." (PMID 20025731, 2009). "Among 38 vimentin-positive tumours, 31 were ER-negative and 31 were PgR-negative, whereas 7 were ER and PgR-positive (p < 0.001)." (PMID 19695088, 2009). "Estrogen receptor (ER) status, progesterone receptor (PR) status, nodal status, tumor size, and grade of malignancy are the classical parameters used to date by clinicians to narrow down prognoses and weight treatment options." (PMID 19740422, 2009). "Although ER- and/or PgR-positive tumours respond poorly to primary chemotherapy in terms of pCR, long-term prognosis of these tumours is consistently better compared with that of ER-negative tumours." (PMID 18941458, 2008). "Tumor size, percentage of positive axillary nodes and expression status for the progesterone receptor, Ki-67 and carbonic anhydrase IX demonstrated independent prognostic significance with respect to relapse-free survival." (PMID 18194560, 2008). "The majority of basal-like tumours lack ER, PgR and HER2 expression (i.e. display a triple-negative phenotype)." (PMID 18612310, 2008). "The striking improvement in terms of pathological complete response (pCR) obtained in endocrine-unresponsive tumours with new schedules of anthracyclines and taxanes has had a lesser impact in ER- and PgR-positive tumours, which obtained pCR up to 10%." (PMID 18941458, 2008). "A significant inverse correlation was found between Skp2 expression and tumor differentiation (P = 0.001), ER expression (P = 0.006), and PgR expression (P = 0.005)." (PMID 18644126, 2008). "We have reported earlier that ER+/PgR-negative tumours are more likely to relapse on tamoxifen, and a number of other laboratory studies report a reduction in PgR expression in ER+ cells that is consistent with acquired tamoxifen resistance." (PMID 19018258, 2008).
tumor (continued). "We have investigated earlier the activity of the combination of a non-anthracycline- and taxane-based chemotherapy with endocrine therapy in a series of patients with ER- and PgR-positive tumours." (PMID 18941458, 2008). "As for protocol, all patients had ER ⩾10% tumours, whereas PgR was positive in 30 out of 36 tumours." (PMID 18941458, 2008). "African-American (A-A) women had significantly larger tumours, lower rates of localised disease and higher rates of oestrogen receptor (ER) and progesterone receptor (PgR) negativity, all of which confer a poorer prognosis." (PMID 18182985, 2008). "More variables characterizing non-compliant cases identified by DTI are number of lymph nodes that are invaded by malignant cells, Progesterone receptor level, DNA index, age, tumor size and Estrogen receptor level." (PMID 18803875, 2008). "No other statistically significant associations between SBEM and established prognostic factors such as tumour size, axillary lymph node status and progesterone receptor were observed." (PMID 18269587, 2008). "Patients with hormonal receptor negative tumours had a 24.3 times higher probability of achieving a pCR than patients with PgR-positive tumours." (PMID 18380893, 2008). "The tumor was highly positive for estrogen receptor (ER) expression (95%), but less than 10% positive for progesterone receptor (PR) expression." (PMID 18826630, 2008). "All but one tumour maintained ER positivity at surgery, while downregulation of PgR was observed in 26 patients." (PMID 17712311, 2007). "Group 1 showed a higher percentage of PgR-positive tumours, whereas group 2 showed a higher percentage of tumours with peritumoural inflammation." (PMID 17848954, 2007). "Our results confirm a possible role for the expression of PgR in determining the endocrine responsiveness of the tumour." (PMID 17712311, 2007). "We also found an association between some histological subtypes of the in situ ductal tumours and Her-2, ER, and PgR expression, whereby the comedo and cribriform subtypes significantly over expressed Her-2 and were ER negative." (PMID 17892570, 2007). "Neoadjuvant antihormonal therapy with an AI is a particularly attractive option for postmenopausal women who wish to attempt breast conservation and have strongly ER- and PgR-positive tumours that are ≥ 3 cm and have low proliferation rates." (PMID 17892469, 2007). "Other studies, however, have reported a higher tumour expression of PgR in patients older than 59 years, as compared to those between 50 and 59 years." (PMID 17892570, 2007). "While the consensus report clearly defines responsive tumours as ER(+)/PgR(+), tumours with uncertain responsiveness as ER(+)/PgR(−), and non-responsive tumours as ER(−)/PgR(−), the classification of ER(−)/PgR(+) tumours has remained unclear." (PMID 17726451, 2007). "It was also of interest to examine changes in PgR score in tumours that initially displayed a decrease in Ki67 at 10–14 days but an increase at 3 months." (PMID 16538221, 2006). "The presence of immunocytochemical staining for AGR2 was cross-tabulated with the established prognostic factors of tumour size, nodal status, histological grade, lymphovascular invasion, ERα and PgR status." (PMID 16598187, 2006). "The greater benefit of an AI in ER+/PgR− patients compared to ER+/PgR+ tumours was significant in the ATAC trial, and was supported by the ABCSG/ARNO trial and to some extent by the IES trial." (PMID 16434989, 2006). "Treatment decisions are based on axillary node status, age, tumor size, histologic tumor type, tumor grade, hormone receptor status (ER, PgR), and coexisting medical conditions." (PMID 16737553, 2006). "In a sub-group of ER/PGR-positive, HER2-negative tumours, expression of HDAC-1 was associated with a better DFS probability then HDAC-1 negative tumours." (PMID 16595007, 2006).
tumor (continued). "Hormone receptor expression was unchanged after treatment in the majority of tumours in this cohort, but a significant minority (10 cases, 8%) displayed a shift in ER or PgR classification at the time of surgery." (PMID 15611798, 2005). "A total of 64% of the patients had tumours with a positive steroid hormone receptor status; that is, they were oestrogen receptor and/or progesterone receptor positive." (PMID 15743506, 2005). "In all, 66% of the tumours were ER positive and/or PgR positive, and 81% were intermediate or high-grade tumours." (PMID 15668703, 2005). "In all, 10 tumours changed hormone receptor classification after chemotherapy (three ER, seven PgR); HER-2 staining changed in nine cases." (PMID 15611798, 2005). "There was a significant correlation between ER and PgR (P<0.0001): 80% of ER− tumours were also PgR−; 75% of tumours showed positivity for both steroid receptors." (PMID 15611798, 2005). "Specifically, multivariate analysis revealed age, grade and PgR negativity as the independent factors distinguishing BRCA1 tumours from familial non-BRCA1/2 tumours." (PMID 15642173, 2005). "Spearman's rank correlation test was used to examine the association between Syk expression in tumours and patients' age, tumour size, tumour grade, estrogen and progesterone receptor status, lymph node metastasis, vascular invasion and clinical outcome." (PMID 15842733, 2005). "Other adverse prognostic factors associated with EFS and OS were treatment with FEC21 as compared to FEC14 nodal status, PgR status, proliferative activity, tumour size, and grading." (PMID 15970926, 2005). "In all, 84% of these tumours were oestrogen receptor positive and 70% were progesterone receptor positive." (PMID 15054466, 2004). "The clinical variables were: grading of tumours, tumour size, lymph node involvement, tumour staging, oestrogen and progesterone receptor levels (76 out of 80 cases), and c-erbB-2 levels (46 cases)." (PMID 15054465, 2004). "Oestrogen and progesterone receptor expression in the cancer cell nuclei was noted in 42 out of 71 and 21 out of 71 tumours, respectively." (PMID 12618880, 2003). "Of these, patients with a tumour rich in one receptor (either ER or PgR) had a better outcome than those with tumours rich in neither receptor." (PMID 12085248, 2002). "Cox multivariate analysis indicated that KLK13 was an independent prognostic variable in the subgroups of patients with Grade I–II tumours and in patients who were oestrogen receptor and progesterone receptor positive, and node positive." (PMID 11986781, 2002). "Neither CCND1 amplification nor CCND1 overexpression without amplification was significantly linked to menopausal status or standard prognostic factors such as macroscopic tumour size, histopathological grade and lymph-node or progesterone receptor status." (PMID 11870541, 2002). "Tumour oestrogens receptor status at diagnosis was determined before treatment in 325 patients (72.1%), and the progesterone receptor status was determined in 321 patients (71.2%)." (PMID 11953845, 2002). "Of the newer variables, PgR (any nuclear staining) was detected in 162 out of 204 tumours available for assay." (PMID 12085248, 2002). "For time to recurrence, the key factors were number of nodes involved, PgR, tumour grade and clinical size." (PMID 12085248, 2002). "In the multivariate analysis as well, vascular endothelial growth factor showed to be an independent predictor of poor relapse-free survival and overall survival (P=0.045 and P=0.029, respectively), in addition to age, tumour size and PgR." (PMID 12232762, 2002). "S100A4 staining was not correlated to the patients' ages at time of presentation, PgR, lymph node involvement or tumour diameter." (PMID 12439718, 2002). "Multivariate models were adjusted for oestrogen and progesterone receptor status, nodal status, patient age, tumour size, DNA ploidy, S phase fraction and receipt of chemotherapy." (PMID 10507775, 1999).